CPT1A (carnitine palmitoyltransferase 1A)
Diseases named in the same sentence as CPT1A in open-access papers (continued):
Sharing a sentence is not in itself a finding about the gene and the disease.
prostate carcinoma (continued). "Combination therapy with etomoxir (an irreversible inhibitor of CPT1A), and orlistat (an irreversible inhibitor of lipases and fatty acid synthase) resulted in a synergistic decrease in viability of prostate cancer cell lines (LNCaP and VCaP) and patient-derived benign and prostate cancer cells." (PMID 37110858, 2023). "Currently, the primary treatments for prostate cancer include diet modification and the use of antioxidants, while CPT1A inhibition may provide novel therapeutic options." (PMID 37033619, 2023). "These facts highlight the therapeutic potential of CPT1A blockade to prevent prostate cancer." (PMID 37033619, 2023). "Several studies highlight the role of CPT1A in prostate cancer." (PMID 29445084, 2018). "Moreover, CPT1A depletion can sensitize prostate cancer cells to anti-androgen treatment, enzalutamide." (PMID 29996946, 2018). "Besides, increased histone acetylation has been observed in prostate cancer cells that over-express CPT1A, suggesting that acetylation may be a means by which CPT1A controls prostate cancer cell proliferation." (PMID 37033619, 2023). "CPT1A-mediated succinylation of SP5 induces transcription of 3-phosphoinositide-dependent protein kinase 1, activating the AKT/mTOR signaling pathway in prostate cancer." (PMID 41219902, 2025). "For example, in melanoma and prostate cancer cells, interferon-γ secreted by CD8+T cells upregulates the expression of CPT1A, thereby promoting resistance to CAR-T cell therapy and contributing to immunotherapy failure." (PMID 41219902, 2025). "Exosomes from prostate cancer cells further impair tumor-infiltrating CD8+ T cells by releasing IL-8, which activates PPARα in receptor cells and subsequently upregulates CPT1A expression in tumor cells, disrupting energy metabolism." (PMID 41219902, 2025). "ETX is an irreversible CPT1A inhibitor and in vivo and in vitro studies have shown that ETX inhibits the growth of prostate cancer tumours." (PMID 37416765, 2023). "It regulated the differentially expressed gene carnitine palmitoyltransferase 1A (CPT1A) and its homolog CPT1B, shown to regulate prostate cancer growth under hypoxic conditions." (PMID 36064320, 2022). "The gene expression data of prostate cancer (PRAD) patients in The Cancer Genome Atlas (TCGA) cohort suggested a moderate positive correlation (r = 0.22; p = 5.7 × 10−8) between HIF1A and CPT1A expression." (PMID 34944922, 2021). "Exposure of prostate cancer cells to PEITC downregulate many fatty acid metabolism proteins, including acetyl-CoA carboxylase 1 (ACC1), fatty acid synthase (FASN) and carnitine palmitoyltransferase 1A (CPT1A)." (PMID 30445746, 2018). "Furthermore, CPT1A directly binds to SP5 and promotes its succinylation, which in turn enhances SP5's binding to the PDPK1 promoter, thereby increasing PDPK1 transcription and promoting prostate cancer progression." (PMID 40070041, 2025). "In the present study, we aimed to explore the relationships between the expression of certain genes (CYP7B1, SRSF-1, FAS, PSMA, ACC-1, CPT1a, and SREBP) and oncological factors in prostate cancer patients with and without diabetes." (PMID 38731981, 2024).
steatosis (31 papers, 2012 to 2025). Increased lipid within the cytoplasm of cells. "We first assessed the impact of liver-specific Cpt1a-deficiency on fasting-induced steatosis with LFD-feeding and found that male and female LKO mice had increased liver weights and hepatic triglycerides, as compared to their respective controls." (PMID 37797918, 2023). "SKK normalized the FFA-stimulated overexpression of SREBP1c, FAS, C/EBPα, and CPT1A genes associated with the induction of steatosis." (PMID 33096687, 2020). "•CPT1a-deficiency drives microvesicular steatosis in periportal hepatocytes." (PMID 37797918, 2023). "High steatosis lines had a rather low expression of genes associated with gluconeogenesis, phospholipid-, and cholesterol biosynthesis with concomitant low expression of CPT1A indicating an additional lower capacity of β-oxidation and thus energy generation." (PMID 33372064, 2021). "Contrary to the phenotype observed in Eva1a-LKO mice, Eva1a overexpression suppressed both transcription and expression of CD36, while enhancing those of CPT1A, thereby mitigating steatosis in the livers of ob/ob mice." (PMID 41306774, 2025). "In contrast, Pro displayed distinct effects on lipogenic gene expression, particularly in its repression of CPT1A, suggesting reduced fatty acid oxidation, a common feature of steatosis." (PMID 40100312, 2025). "With excessive liver lipid accumulation, down-regulation of CPT1A expression leads to an imbalance between β-oxidation and steatosis, resulting in lipid per-oxidation." (PMID 38601914, 2024). "In the present study, the protein expression levels of PPARα and CPT1A were decreased by HFD-induced steatosis, suggesting that reduced β-oxidation is one of the vital causes of steatosis." (PMID 37033263, 2023). "After treatment with calcitriol, HepG2 cells in the model group showed improved intracellular steatosis, which was accompanied with higher protein expression levels of PPARα and CPT1A." (PMID 37033263, 2023). "Data from the literature report that the expression of Cpt1a mRNA is up-regulated in CCl4-induced HF in mice and promote oxidative stress, while the silencing of Cpt1a (Cpt1a−/− mouse) protects against steatosis in CCl4-treated animals." (PMID 36579532, 2022). "In this study, only CPT2 was overexpressed, but in a previous study, we reported that the intake of lycopene from tomato juice increased the mRNA abundance of CPT1A, together with the carnitine content, in the liver of rats with steatosis." (PMID 30987167, 2019). "It is also likely that the greater decrease in Cpt1a, which is rate limiting for FA β-oxidation, in Nrf2−/− livers than in Nrf2+/+ livers contributes to increased steatosis in the mutant animals." (PMID 24958099, 2014). "Although AMPKα deactivation was observed in both ADH− and ADH+ deer mice fed 3.5% EtOH, a differential expression of CaMKKβ, ACC1 and CPT1A found in ADH− deer mice fed 3.5% EtOH is particularly important to understand the metabolic basis of EtOH-induced steatosis and liver injury." (PMID 31581705, 2019). "Treatment of HepG2 cells with 2 mM FFA induced the overexpression of steatosis associated C/EBPα (untreated cells (UC): 1.24 ± 0.82; 0 μg/mL: 9.91 ± 0.88), FAS (UC: 1.34 ± 0.94; 0 μg/mL: 4.1 ± 0.48), SREBP1c (UC: 0.61 ± 0.19; 0 μg/mL: 1.84 ± 0.53), and CPT1A (UC: 1.17 ± 0.64; 0 μg/mL: 5.43 ± 0.56)." (PMID 33096687, 2020). "Expression of hepatic genes related to lipid metabolism (Cpt1a, Atgl, Mgl, Dgat2, Srebp, Plin2) and OS (catalase, Edem) were modulated by FB23, although hepatic steatosis remained unchanged." (PMID 39984825, 2025). "Our steatosis model exhibited no significant impact on either Carnitine palmitoyltransferase 1a (CPT1a) or Carnitine palmitoyltransferase 2 (CPT2) expression." (PMID 38474427, 2024). "Along with inhibition of CPT1A, increased ACC1 and other lipogenesis pathways, mobilization of lipids to the liver and decreased lipophagy may have contributed to EtOH-induced steatosis in our deer mouse model." (PMID 31581705, 2019).
steatosis (continued). "Additionally, we observed micro- and macrovesicular lipid inclusions within the hepatocytes of HFI, with elevated steatosis volume, plasma TAG and cholesterol concentrations, and decreased expression of beta-oxidation-related genes (Ppargama, Pgc1a, and Cpt1a)." (PMID 38822155, 2024). "In this study, the patients with steatosis had lower levels of PPARα, ACOX1 and CPT1A than the ones without steatosis." (PMID 29022907, 2017). "Both IHC analysis and western blot assays showed the proteins of CYP7A1, PGC-1α, PPARα, CPT1A and ACOX1 were decreased in livers tissues from patients with steatosis when compared with ones without steatosis." (PMID 29022907, 2017). "Notably, SREBP1 and FASN did not change significantly in the 3D and mouse steatosis models, whereas PGC1A/CPT1A increased in both, consistent with an early metabolic response favoring fatty acid oxidation over robust repression of de novo lipogenesis." (PMID 41035773, 2025). "Ppara, but not Cpt1a, was significantly upregulated by HFHC feeding in the clodronate-treated group but not in the vehicle-treated group, which might in part have contributed toward the attenuation of steatosis by activating β-oxidation." (PMID 33664289, 2021).
colorectal cancer (29 papers, 2018 to 2025). A primary or metastatic malignant neoplasm that affects the colon or rectum. "Meanwhile, studies have shown that CPT1A mediated fatty acid oxidation can promote metastasis of colorectal cancer cells by inhibiting nest loss apoptosis." (PMID 38169514, 2024). "CAFs up‐regulate carnitine palmitoyltransferase 1A (CPT1A) to cause reduction of fatty acid oxidation, leading to peritoneal metastasis of colorectal cancer." (PMID 34977870, 2021). "For example, carnitine palmitoyltransferase 1A (CPT1A) is a key molecule that promotes oxaliplatin resistance in colorectal cancer." (PMID 39942602, 2025). "In colorectal cancer, CPT1A enhances metastatic potential by supporting cancer stem cell properties." (PMID 40867868, 2025). "Several studies have shown that valine-containing protein in colorectal cancer binds to histone deacetylase 1, promoting the degradation of valine-containing protein, activating the transcription of CPT1A, and further promoting the growth of tumors." (PMID 41219902, 2025). "According to research, CPT1A-mediated fatty acid oxidation can encourage the spread of colorectal cancer cells by impairing the process of cell death." (PMID 38329444, 2024). "High expression of CPT1A has been correlated with resistance to oxaliplatin, while low expression was observed in oxaliplatin-sensitive colorectal cancer cells." (PMID 39355533, 2024). "In-depth investigations have revealed that CPT1A-mediated fatty acid oxidation activation enabled colorectal cancer cells to resist anoikis." (PMID 38693136, 2024). "For instance, CPT1A which controls fatty acid oxidation can confer anoikis resistance and promote colorectal cancer metastasis." (PMID 39391236, 2024). "For instance, studies have demonstrated that CPT1A-mediated fatty acid oxidation promotes metastasis of colorectal cancer cells by inhibiting anoikis." (PMID 37688768, 2023). "The elevated expression of CPT1A has been observed in metastatic tumors compared to primary tumors of colorectal cancer patients." (PMID 37601653, 2023). "Consistently, it has been demonstrated that the knockdown of CPT1A reduces fatty acid oxidation and leads to apoptosis in colorectal cancer cells." (PMID 37686221, 2023). "It has also been shown that in colorectal cancer, the fatty acid oxidation pathway is activated in detached cells that are able to leave the primary tumour and that high levels of CPT-1A are seen in metastatic colorectal cells." (PMID 36180554, 2022). "CPT1A-mediated fatty acid oxidation promotes the metastasis of colorectal cancer cells by inhibiting anoikis." (PMID 35958927, 2022). "Analysis of Oncomine data revealed an obvious decrease in CPT1A mRNA expression in colorectal cancer compared with that in normal tissues." (PMID 33528867, 2021). "The upregulated CPT1A promoted metastasis in colorectal cancer by activating fatty acid oxidation, indicating that CPT1A is closely associated with tumor metastasis." (PMID 33381539, 2020). "Recently, researchers observed that CPT1A expression was significantly upregulated in colorectal cancer." (PMID 33381539, 2020). "CPT1-A-mediated FAO prevents anoikis in colorectal cancer cells, which is essential for survival during metastasis." (PMID 33291682, 2020). "Preliminary evidence indicates that CPT1A may be a potential biomarker for chemotherapy resistance in colorectal cancer and that targeted modulation of mtDNA copy number may represent an effective strategy to reverse such resistance." (PMID 41293266, 2025). "Moreover, research has demonstrated that reducing CPT1A levels in colorectal cancer cells can reverse their resistance to oxaliplatin by inhibiting FAO." (PMID 41293266, 2025). "Similarly, CPT1A expression level was elevated in colorectal cancer, particularly within metastatic sites." (PMID 38693136, 2024). "CPT1A promoted metastasis in colorectal cancer cells by inhibiting anoikis." (PMID 38226966, 2024).
colorectal cancer (continued). "For example, CPT1A could confer anoikis resistance and facilitate metastasis in colorectal cancer (CRC) through the regulation of fatty acid oxidation." (PMID 34992654, 2021). "Remarkably, colorectal cancer cells not only express CPT1-A, they also express CPT1-C." (PMID 33291682, 2020). "Furthermore, the metastatic tumors generated from colorectal cancer showed increased levels of CPT1-A expression." (PMID 33291682, 2020). "In addition, colorectal cancer cells display a reduced capacity to oxidize butyrate compared to normal colonocytes, which could result from diminished intracellular carnitine and CPT1A levels." (PMID 29930765, 2018). "In colorectal cancer murine models on high-fat diets, enrichment of Corynebacterium ST1911 activates CPT1A and downstream extracellular signal-regulated kinase (ERK) signaling, promoting malignant progression and disrupting lipid homeostasis." (PMID 41219902, 2025). "Therefore, on the basis of the integration of our current findings with previous research evidence, we hypothesize that the upregulated expression of CPT1A in drug-resistant colorectal cancer cells may serve as a potential biomarker for chemotherapy resistance in this disease." (PMID 41293266, 2025). "We investigated the prognostic relevance of CPT1A and POLG expression in colorectal cancer (CRC) using publicly available oncology databases." (PMID 41293266, 2025). "In colorectal cancer, several genes in the FAO pathway, especially CPT1A, are activated through multiple pathways and are closely associated with the metastasis of colorectal cancer cells." (PMID 39596847, 2024). "Targeting CPT1A represents a previously overlooked approach, synergistic with IKE-induced MDSC actual ferroptotic death in melanoma, lung carcinoma, and colorectal carcinoma." (PMID 39596904, 2024). "In recent years, many studies reported that regulation of the key enzyme CPT1A in FAO affects the occurrence and development of various tumours, such as nasopharyngeal carcinoma and colorectal cancer." (PMID 37416765, 2023). "In colorectal cancer (CRC), CPT1A has been shown to strengthen resistance to anoikis and eliminate reactive oxygen species (ROS), thus promoting CRC cell metastatic capacity." (PMID 36632454, 2023). "In colorectal cancer, TAM-derived GDF15 increases CPT1A expression, which reduces chemosensitivity." (PMID 41219902, 2025). "Recently, it has been shown that 2,6-dihydroxypeperomone B extracted from plants can selectively bind covalently to Cys96 of CPT1A and disrupt the integrity of the mitochondrial membrane by affecting its formation of the VDAC1 complex, thereby inducing apoptosis in colorectal cancer cells." (PMID 39596847, 2024). "Furthermore, we confirmed that carnitine palmitoyltransferase IA (CPT1A), a rate‐limiting enzyme of FAO, was expressed at significantly low levels in patients with PM colorectal cancer, as determined by RT‐qPCR, IHC, and GEO dataset analysis." (PMID 33528867, 2021).
nasopharyngeal carcinoma (28 papers, 2020 to 2025). A carcinoma arising from the nasopharyngeal epithelium. "High CPT1A levels were associated with worse OS of nasopharyngeal carcinoma patients post-radiotherapy." (PMID 39533394, 2024). "Increased expression of CPT1A in radiation-resistant nasopharyngeal carcinoma (NPC) cells is significantly associated with poor overall survival of NPC patients." (PMID 40814339, 2025). "PPARγ coactivator-1α forms a complex with CCAAT/enhancer-binding protein β to promote CPT1A transcription, driving CPT1A overexpression and radioresistance in nasopharyngeal carcinoma." (PMID 41219902, 2025). "In nasopharyngeal carcinoma cells, shRNA-mediated knockdown of CPT1A significantly inhibits proliferative capacity, which is closely linked to energy deficiency caused by impaired fatty acid oxidation." (PMID 41378259, 2025). "CPT1A-targeted therapy was shown to boost radiation therapy sensitivity of nasopharyngeal carcinoma since CPT1A-Rab14 interaction promotes radiation resistance." (PMID 40361394, 2025). "Blunting CPT1A sensitized nasopharyngeal cancer cells to radiotherapy via triggering mitochondrial apoptosis." (PMID 39533394, 2024). "For example, it has been demonstrated that PGC1α binding to CCAAT/enhancer binding protein β (CEBPβ) can induce the upregulation of Cpt1a gene in nasopharyngeal carcinoma cells." (PMID 37524243, 2023). "Radiation resistance of nasopharyngeal carcinoma has been attributed to the PGC1α/C/EBPβ/CPT1A axis, and C/EBPβ is required for therapeutic resistance in NRF2-activated non-small cell lung cancer." (PMID 36761942, 2023). "Among the nasopharyngeal carcinoma cases (n = 33) in the tissue chip, there were 14 patients with high CPT1A expression, and the percentage was 42.4%." (PMID 35411000, 2022). "The in vitro experiments demonstrate that the PPAR coactivator-1α (PGC1α) binds to CCAAT/enhancer binding protein β (CEBPB) and increases FAO regulated by CPT1A in nasopharyngeal carcinoma (NPC) cells." (PMID 35216362, 2022). "Targeting CPT1A-mediated FAO has also been shown to sensitize nasopharyngeal carcinoma to radiation therapy." (PMID 36233047, 2022). "CPT1A was shown to facilitate the trafficking of FAs between the mitochondria and cytoplasm, which promoted FA utilisation in the acceleration of nasopharyngeal carcinoma." (PMID 34976793, 2021). "Our previous study found that CPT1A promotes radiation-resistance in nasopharyngeal carcinoma, and gene ontology enrichment analysis showed that exocytosis is predicted as the most associated biological process for CPT1A-binding proteins." (PMID 33858374, 2021). "Nasopharyngeal carcinoma studies have confirmed that a reduction in the expression of CPT1A can improve the efficacy of radiotherapy for the disease." (PMID 33381539, 2020). "It has been reported that targeting CPT1A could be a beneficial regimen to improve the therapeutic effects of radiotherapy in nasopharyngeal carcinoma (NPC) patients." (PMID 38003694, 2023). "In the present study, we found that CPT1A is a determining factor for the abnormal activation of FAO in nasopharyngeal carcinoma (NPC) cells." (PMID 35411000, 2022). "The PGC1α/CEBPB/CPT1A axis, which enhances lipid β-oxidation, increases ATP and NADPH levels and promotes cellular radiation resistance in nasopharyngeal carcinoma." (PMID 39607749, 2024). "So, CPT1A targeting may be a good way to improve radiotherapy’s beneficial efficacy in patients with nasopharyngeal carcinoma (NPC)." (PMID 36608061, 2023). "PGC-1α PGC1α binds to CCAAT/enhancer binding protein β (CEBPB) to enhance CPT1A transcription, resulting in activation of FAO through PGC1α/CEBPB/CPT1A/FAO signaling axis, which can promote radiation resistance of nasopharyngeal carcinoma (NPC)." (PMID 37033619, 2023). "For example, in the case of nasopharyngeal carcinoma cells, CEBPB binds to PPAR coactivator-1α and promotes the transcription of CPT1A, which ultimately increased the level of fatty acid oxidation." (PMID 36225942, 2022).
nasopharyngeal carcinoma (continued). "In another study, PGC-1α, the key transcription coactivator regulating CPT1A and CPT1B, binds to the transcription factor CEBPB to promote CPT1A expression, which enhances FAO activity to maintain the high NADPH/NADP+ ratio, contributing to radiation resistance of nasopharyngeal carcinoma cells." (PMID 35936710, 2022).